BRAF (B-Raf proto-oncogene, serine/threonine kinase)
Diseases named in the same sentence as BRAF in open-access papers (continued):
Sharing a sentence is not in itself a finding about the gene and the disease.
melanoma (continued). "In addition, the changes in ABCB5 differed between the early passages and the late passages of melanoma cells in response to BRAF treatment." (PMID 29929490, 2018). "BRAF and MAP inhibitors have shown efficacy also in BRAF V600 mutated melanoma." (PMID 29492238, 2018). "In addition, the percentage of MMP-9 serum variations at different times during the treatment with BRAF inhibitors were analyzed in melanoma patients." (PMID 30154717, 2018). "In addition to the HER2-breast cancer (#5) and BRAF–melanoma (#12) co-modules, other cancer-related co-modules were selected, such as those representing the hypermutated phenotype (#3) and responders to receptor tyrosine kinase inhibitors (#28)." (PMID 29950679, 2018). "Therefore, SOX10 depletion can sensitize mutant BRAF melanoma cells to Vemurafenib in vitro and in vivo." (PMID 29295999, 2018). "In addition, we identified two different BRAF mutations, c.1780 G>A (p.Asp594Asn) which results in an inactivation of BRAF gene and c.1798_1799GT>CG (p.Val600Arg), which rarely occurs in melanoma." (PMID 30181807, 2018). "An example is the successful experience with inhibitors of the MAPK pathway in melanoma, where highly selective inhibitors of BRAF and MEK1/2 kinases have shown antitumor responses in both preclinical settings and have been approved for use in BRAF or NRAS mutant melanoma." (PMID 29545922, 2018). "In addition, the combination of ipilimumab and nivolumab has been approved in patients with wild-type v-Raf murine sarcoma viral oncogene homolog B (BRAF) metastatic or unresectable melanoma." (PMID 29441072, 2018). "We have selected a panel of eight human melanoma cell lines to further characterize the potential effects of leflunomide as an anti-melanoma drug, where half habour the BRAFV600E mutation and the remainder are wildtype for BRAF (BRAFWT)." (PMID 29423085, 2018). "This suggests that melanomas resistant to BRAF inhibitors might be treated with the potent MEK inhibitor trametinib." (PMID 30053879, 2018). "However, as the cell line used in this study is BRAF wildtype it is still possible that CEACAM1 signaling affects IGFBP7 expression in certain subsets of patients (e.g. patients with BRAF wildtype melanoma)." (PMID 30089785, 2018). "We also discuss how, in our opinion, these flaws led Díaz-Martínez and colleagues to incorrect conclusions about the biological role that miR-204 and miR-211 play in melanoma and about the terms of their involvement in the phenomenon of resistance to BRAF inhibitors." (PMID 30234146, 2018). "Given that the clinical role of the MAPKi is widely documented in melanoma, we first tested whether BRAF and MEK inhibitors possess a differential antitumor activity between CSCs and their more differentiated counterparts." (PMID 30558661, 2018). "In addition, the changes of ABCB5 differed between the early passages and the late passages of melanoma cells in response to BRAF inhibitor treatment." (PMID 29929490, 2018). "Mutations associated with RAF family are frequently associated with BRAF and even though BRAF mutations are genetic drivers in a wide range of tumors, they are mainly found in cancers that harbor RAS mutations, such as malignant melanoma, colorectal and thyroid carcinomas." (PMID 29455659, 2018). "BRAF, a member of the RAF family, often mutates at the V600 codon in melanoma (V600E, 80% of mutations; V600K, 16% of mutations; and V600D/R, 3% of all mutations in melanoma)." (PMID 30274263, 2018). "Taken together, these results suggest that biguanides, such as metformin, could be used in combination with targeted therapies against BRAF or with immunotherapies to synergize treatment effects on melanoma cells." (PMID 30186236, 2018). "Therefore, Ole represents a natural product able to potentiate a wide array of chemotherapeutics against BRAF melanoma cells affecting the pAKT/pS6 pathway." (PMID 30544808, 2018).
melanoma (continued). "A recently reported study tested neoadjuvant dabrafenib and trametinib in BRAF-mutant melanoma." (PMID 30352626, 2018). "Although acquired activation of PI3K signalling occurs in a subset of melanomas it remains unclear whether PI3K activation alone is sufficient for the development of BRAF inhibitor resistance." (PMID 30237495, 2018). "Importantly, TpeL inhibited the paradoxical activation of the MAP kinase pathway induced by the BRAF inhibitor Vemurafenib in the human melanoma cell line SBCL2." (PMID 29662661, 2018). "In addition, lung cancer, melanoma, and breast cancer with high BM probability have respective molecular mechanisms, such as ALK rearrangement, BRAF mutation, and D1‐CDK4/6 complex formation." (PMID 29992751, 2018). "Thus, our data provide the foundation to investigate the presence and loss of pRb-Ser780 as a biomarker of acquired resistance to BRAF/MEK inhibition and a biomarker of response to BRAF/MEK/CDK4/6 therapy in BRAFV600E-mutant melanomas, respectively." (PMID 29541385, 2018). "A 53‐year‐old man was randomized in the DC‐MEL trial (EudraCT number: 2011‐001410‐33) in May 2014 after the resection and radiation of lymph node metastases of a BRAF wild‐type melanoma." (PMID 30133176, 2018). "Here we asked whether high iNAMPT levels in BRAF-resistant (BiR) melanoma cells were paralleled by elevated extracellular concentrations of the enzyme." (PMID 29721178, 2018). "This provided initial evidence that BRAF interacts with HSP90 in human melanoma cells." (PMID 29481571, 2018). "Particularly, in the melanoma sub group, BRAF mutation did not impact outcome of stereotactic radiotherapy (p = 0.41)." (PMID 30055640, 2018). "These have been particularly recalcitrant to treatment, with overall survival times that are shorter than those of patients with melanoma harboring BRAF mutations, and do not respond to BRAFV600 inhibitors such as vemurafinib and dabrafenib." (PMID 28157711, 2017). "Intermittent dosing of BRAF/MEK inhibitor combinations has also been suggested to delay the emergence of resistance in BRAF mutant melanoma, and this is currently being investigated in a randomized phase 2 clinical trial of continuous versus intermittent dosing of dabrafenib with trametinib." (PMID 29100459, 2017). "It is also important to use nanotechnology for the development of new electrospun fibers that might work as BRAF inhibitors for the treatment of melanoma." (PMID 28303522, 2017). "A375 cells are among the most widely used xenograft models for BRAF‐mutant melanoma." (PMID 28069687, 2017). "Because BRAF oncogene levels appear to regulate melanoma neuronal differentiation and tumor progression, blockade of BRAF production with vemurafenib and forced MAP2 expression by demethylation with decitabine could induce apoptosis in metastatic melanoma." (PMID 29179510, 2017). "The mean age (P = 0.312) and gender (P = 0.553) were not significantly different between melanoma patients harbouring BRAF V600E mutation with or without EZH2 gain." (PMID 29202777, 2017). "In untreated melanoma patients without a BRAF V600E mutation, nivolumab treatment alone had a 72.9% overall survival at 1 year compared to 42.2% with dacarbazine treatment." (PMID 28730140, 2017). "This paradoxical proliferation was reproducibly observed in the A375‐sensitive melanoma cell line as opposed to some other sensitive or resistant BRAF‐mutated cell lines." (PMID 28573821, 2017). "However, Ranzani and colleagues also claim that most BRAF/NRAS wild‐type melanomas are highly sensitive to MEK inhibition irrespectively of the NF1 protein level." (PMID 28267273, 2017). "The findings of the presence of intraepidermal nests, DEJ nest, bright dots, in the absence of junctional thickening and absence of meshwork is highly suggestive that the melanoma in question will harbor a BRAF V600E mutation." (PMID 28662062, 2017).
melanoma (continued). "Thus combinations of BRAF and MEK inhibitors have been developed, and were shown to induce longer progression free survivals (PFS) of patients with BRAF mutated melanomas." (PMID 28668077, 2017). "In melanoma, a proportion of patients’ tumors have constitutively activated BRAF." (PMID 29375561, 2017). "On this ground, we were prompted to test the antimetastatic properties of the more soluble NBD derivative, MC3181, against melanoma cells lines derived from the primary lesion (WM115) and a skin metastasis (WM266.4) of a single patient harboring a BRAF-V600D mutation." (PMID 28107182, 2017). "Previously, we identified the plasma membrane Ca2+ ATPase 4b (PMCA4b) as a metastasis suppressor in BRAF-mutant melanomas and found that mutant BRAF inhibition increased the expression of the pump, which then inhibited the migratory and metastatic capability of the cells." (PMID 28596940, 2017). "Thus, our data confirm that fibroblasts can protect melanoma cells from BRAF inhibition through reactivation of the MAPK pathway." (PMID 28450382, 2017). "While single alteration, either LKB1 loss or BRAF V600E, fails to enhance melanoma cells invasion ability." (PMID 29371951, 2017). "Similarly, BRAF (V600E), the most common mutation in melanoma, correlates with DRP1 phosphorylation in melanoma tumor tissues, whereas MAPK inhibition reverses DRP1-mediated mitochondrial fission, and sensitizes cells to mitochondrial-targeting drugs." (PMID 28448495, 2017). "Interestingly, we found that the EPE peptide was effective not only in reducing the viability of many BRAF mutant melanomas, but it also affected some cell lines bearing NRAS and/or NF1 mutations as well." (PMID 29180761, 2017). "Here, we also observed that cell lines, both BRAF- and PTEN-mutated, were the most sensitive towards WP760, however further studies are required to prove that inhibition of IGF1R indeed contributes to WP760 anti-melanoma activity." (PMID 28417283, 2017). "To investigate this, we performed an siRNA-mediated knockdown of DUSP6 in BRAF wild type melanoma." (PMID 28423600, 2017). "Therefore, once BRAF-mutant melanoma cells become resistant to BRAF inhibitors, not only do the cells evade inhibitory effects of these drugs, but their ability to metastasize was also enhanced." (PMID 28708099, 2017). "Indeed, melanoma cells with poor EGFR background are highly responsive to BRAF inhibitors, whereas colon carcinoma cells exhibit a rapid feedback activation of EGFR phosphorylation, being characterized by high EGFR expression." (PMID 29033690, 2017). "Our data demonstrated that COX-2 is involved in the proliferation of melanoma cells since treatment of melanoma cells with or without BRAF/NRAS mutations with the COX-2 inhibitor celecoxib inhibits their proliferation and induces cell death." (PMID 28231855, 2017). "Similar effects were noted in both NRAS and BRAF mutant melanoma cells following Ets-1 or Usp9x KD." (PMID 28198367, 2017). "Thus, our findings indicate a probable explanation on LKB1 function as a tumor suppressor in melanoma and a new therapeutic strategy for melanoma by targeting on BRAF and LKB1 together." (PMID 29371951, 2017). "Indeed, the combination of dabrafenib and trametinib improved anti-tumor activity and survival in BRAF mutant melanoma patients." (PMID 29180761, 2017). "Although this BRAF mutation can play a significant role in melanoma development, it is not responsible for the development of these tumours." (PMID 28708099, 2017). "Current strategies for BRAF-V600E melanomas that delay, but have yet to eliminate acquired resistance to BRAFi include combinatorial therapy with BRAFi and MEKi, co-targeting of the MAPK and PI3K pathways, and the combination of small molecule inhibitors with immunotherapy." (PMID 29156677, 2017).
melanoma (continued). "Anyway, one has also to be careful in translating results from animal models into the human practice, as in a human trial involving patients with different types of advanced cancer, a patient presenting with a BRAF positive melanoma was the one which benefited the most." (PMID 28915665, 2017). "In other words, if both parameters are absent there is a high likelihood that the melanoma will harbor the BRAF V600E mutation." (PMID 28662062, 2017). "In a phase 3 trial, median PFS was 12.3 months for cobimetinib plus vemurafenib versus 7.2 months for vemurafenib alone, and these data supported the use of combination as a standard first-line approach to improve survival in patients with advanced BRAF V600-mutant melanoma." (PMID 28954413, 2017). "We observed responses in patients with BRAF‐WT melanoma, including a complete response." (PMID 28719152, 2017). "RAS/MAPK pathway dysregulation has been identified as a key culprit in non-familial melanoma, leading to the discovery of BRAF and NRAS as the most commonly mutated genes." (PMID 28637487, 2017). "Therefore, we set out to explore new factors and regulatory mechanisms of therapy resistance by profiling chemoresistant BRAF wild-type melanoma cells." (PMID 28112719, 2017). "While many mutations have been identified in melanoma, the most common is the BRAF V600E mutation, which is seen in approximately 50% of cutaneous melanomas Studies have shown that BRAF mutated melanomas tend to develop in younger individuals as compared to BRAF wild type melanomas." (PMID 28662062, 2017). "BRAF mutations, and especially BRAFV600E, are an early and very frequent event in melanoma." (PMID 29064423, 2017). "Interestingly, the expression of ER stress markers compatible with a chronic condition has been revealed not only in oncogenic BRAF melanoma cell lines but also in patients who failed the clinical treatment." (PMID 28491820, 2017). "Similarly, in primary melanoma, patients with high expression of BRAF protein had significantly worse OS and disease-specific 5-year survival (n = 370)." (PMID 29176861, 2017). "Interestingly, combination of CK2 inhibitor CX-4945 and BRAF inhibitor vemurafenib additively inhibited proliferation in BRAF mutant patient-derived melanoma cell lines." (PMID 28134850, 2017). "We observed previously that DET or DETD-35 treatment could induce the production of reactive oxygen species (ROS) in mouse TS/A mammary cancer cells or human BRAF mutant A375 melanoma cells." (PMID 28915644, 2017). "However, despite promising drug targets and success in pre-clinical testing, only two MEK inhibitors, trametinib (Mekinist) and cobimetinib (Cotellic), have been approved, both for the treatment of BRAF-mutant melanoma." (PMID 28474232, 2017). "Thus, some NRAS and BRAF mutant melanomas were sensitive to the EPE peptide, while others were either partially sensitive or not sensitive at all." (PMID 29180761, 2017). "NRAS mutant melanomas rarely harbour either mutations in, or silencing of the negative regulator of the PI3K pathway, phosphatase and tensin homologue and exhibit lower levels of constitutive AKT signalling than those with BRAF mutations." (PMID 28497782, 2017). "In addition, despite the successes in treatment of melanoma with BRAF inhibitors, intrinsic or acquired resistance to BRAF inhibitors still were the main problems which need to be solved." (PMID 29371951, 2017). "We have previously found that both DET and/or DETD-35 could significantly induce the generation of ROS in TS/A(ER+) mammary cancer cells, MDA-MB-231 cells or human BRAF mutant A375 melanoma cells." (PMID 28706483, 2017). "We propose that tumor cells in melanoma patients that have gained resistance to BRAF/MEK inhibitors may display the same feature." (PMID 29050218, 2017). "BRAFV600E melanoma treated with BRAF inhibitors may acquire resistance through flexible switching between different RAF isoforms capable of reactivating the ERK pathway, upregulating ARAF or CRAF." (PMID 29100459, 2017).
melanoma (continued). "Although significant advances have been made in the development of new therapies for melanoma, especially in targeted and immunotherapy such as BRAF/MEK inhibitors and checkpoint inhibitor blockade therapies, more than half of patients with advanced melanoma succumb to the disease." (PMID 29285235, 2017). "The phase 1 study has shown a manageable toxicity profile in patients with BRAF V600-mutant melanoma and the ongoing phase 2 study will further evaluate safety and efficacy of this triple combination as a first-line therapy for BRAF-mutant melanoma." (PMID 28954413, 2017). "Indeed, the MEK inhibitor trametinib is recommended as monotherapy and in combination for patients with BRAF V600 mutant melanoma." (PMID 28424891, 2017). "Identification of mutations in the gene encoding the serine/threonine-protein kinase, BRAF, and constitutive activation of the mitogen-activated protein kinase (MAPK) pathway in around 50% of malignant melanomas have led to the development and regulatory approval of targeted pathway inhibitor drugs." (PMID 29100459, 2017). "Moreover, it is not obvious that a mutated gene that behaves as a driver in a context does act similarly in a different tumor, as shown by the V600E BRAF mutants that respond to BRAF inhibitors in 80% of melanomas but only in 5% of colon cancers." (PMID 28915702, 2017). "When bypassing BRAFV600E activity, resistant melanomas often exhibit reactivation of the interconnected MAPK and PI3K/Akt axes, associated with BRAF-independent reactivation of MAPK (caused in some cases by enhanced CRAF), elevated PDGFR, and remodeling of the cancer stroma." (PMID 29050198, 2017). "Moreover, a collection of BRAF V600E mutant melanoma cell lines were used to evaluate the phospho-BMK1 in the CIBM resistant cells, which were built." (PMID 28387310, 2017). "Moreover, 4 of 7 melanoma patients with WT BRAF too exhibited significant downregulation of IDH2 levels." (PMID 29290954, 2017). "The most clinically significant drugs bind RAF and MEK kinases in BRAF‐mutant melanomas." (PMID 29175850, 2017). "Therefore, a combination therapy targeting BRAF V600 mutations (Dabrafenib or Vemurafenib) as well as MEK (Trametinib or Cobimetinib) has been approved in 2015 for use in stage III and stage IV melanoma patients." (PMID 28595656, 2017). "However, in contrast to TNF, which has been shown to directly prevent melanoma cell death in the presence of BRAF signaling inhibition, IL-1β cannot prevent cell death when BRAF signaling is inhibited." (PMID 28450382, 2017). "Thus, at the concentration and exposure time used in our experiments, treatment with the Hsp90 inhibitor 17-AAG and the BRAF inhibitor vemurafenib led to induction of melanoma cell re-differentiation and increased cellular melanin levels." (PMID 28811486, 2017). "Conversely, CK2α knockdown sensitized BRAF-mutant melanoma cells to vemurafenib." (PMID 28134850, 2017). "That is to say, BRAF V600E mutation status in melanoma should not be looked as the sole marker for BRAF targeted therapy." (PMID 29371951, 2017). "As expected for a tumor suppressor, the knockdown either promoted cell growth or did not exert any effect, while the same knockdown in BRAF V600E melanoma with high DUSP6 expression caused cell death via induction of apoptosis." (PMID 28423600, 2017). "BRAF/NRAS wild-type and NF1 mutant melanomas are strongly associated with UV damage, as evidenced clinically by the higher degree of solar elastosis and, at a molecular level, by a high proportion of C > T transitions at pyrimidine dimers and more frequent tandem CC>TT transitions." (PMID 28637487, 2017). "Moreover, PCR1 component BMI1 was shown to contribute to the induction of melanoma gene signatures correlating with metastasis as well as chemo-resistance to BRAF-inhibitors." (PMID 28978033, 2017). "However, the potential effect of BRAF/MEK inhibitors on the interaction between melanoma cells and the immune system seems paradoxical." (PMID 29050218, 2017).